USP18 (ubiquitin specific peptidase 18)
Diseases named in the same sentence as USP18 in open-access papers (continued):
Sharing a sentence is not in itself a finding about the gene and the disease.
tumor (continued). "Engrafted tumors were harvested from athymic mice and USP18 expression in the USP18 stably transfected tumor-forming cells was detected." (PMID 26555296, 2015). "To determine how tumor cell USP18 affects these cells and thus the immune response, we injected B16-OVA-GFP or B16-OVA-USP18 tumor cells into C57BL/6 mice that were depleted of CD4+ or CD8+ T cells or NK cells and monitored tumorigenesis." (PMID 24884733, 2014). "Western blot analysis showed that IFN-γ induced USP18 protein expression in other tumor cell lines such as 4 T1 and EMT6 tumor cells." (PMID 24884733, 2014). "That endogenous IFN signaling through USP18 controls tumorigenesis is evidenced by tumor growth in the Ifng-/- mice after inoculation with B16-OVA-USP18 or B16-OVA-shUSP18 tumor cells." (PMID 24884733, 2014). "Manipulation of USP18 expression not only induces possible anti-apoptotic activity in some cancers, but also change the tumor cell sensitivity to immunotherapy." (PMID 24884733, 2014). "At day 5, activated OT-1 CTLs were adoptively transferred to the mice, together with intra-tumor injection of adenovirus vector expressing USP18 (Ad-USP18)." (PMID 24884733, 2014). "Mechanistically, USP18 expression in tumor cells modulated immune-cell population and phenotype in tumor microenvironment." (PMID 24884733, 2014). "Further studies will be performed to investigate the influence of Ad-USP18 on immune cells in tumor microenvironment." (PMID 24884733, 2014). "Detailed analysis of the immune status in tumor-bearing mice showed that Ad-USP18 significantly increased the duration of CTL persistence in the spleen and tumor sites of tumor-bearing mice." (PMID 24884733, 2014). "Ectopic expression of USP18 in tumor cells suppressed tumorigenesis and antitumor immune response whereas inhibition of USP18 expression promoted tumorigenesis and immunosurveillance." (PMID 24884733, 2014). "Mechanistic studies demonstrated that USP18 suppressed tumor cell-mediated immune inhibition by activating T cells, inhibiting T-cell exhaustion, and reducing dendritic cell tolerance, thus sensitizing tumor cells to immunosurveillance and immunotherapy." (PMID 24884733, 2014). "To explore USP18 function in immune suppression, we analyzed the immune status in the tumor microenvironment after USP18 overexpression in tumor cells (B16-OVA-USP18), which were then intravenously injected in C57BL/6 mice." (PMID 24884733, 2014). "The novel finding in this study is the discovery that the ubiquitin-specific peptidase USP18 can be induced by IFN-γ in tumor cells and plays important roles in inhibiting tumorigenesis and antitumor immunity." (PMID 24884733, 2014). "Our study showed that USP18 expression in tumor cells significantly suppressed the expression of molecules responsible for inhibiting CTL activity during immunotherapy." (PMID 24884733, 2014). "To examine exogenous IFN signaling, such as CTL secretion of IFN-γ, we performed adoptive transfer of activated OT-1 cells, which resulted in stronger USP18 expression in tumor cells in vivo." (PMID 24884733, 2014). "Our study showed that USP18 expression in tumor cells regulated tumorigenesis and IFN-γ secretion by exogenous CTLs as part of the anti-tumor immune response." (PMID 24884733, 2014). "Using our B16 tumor model, we co-administered pmel-1 CTLs, Ad-USP18, IL-2 and dendritic cells into tumor." (PMID 24884733, 2014). "We assessed USP18 mRNA and protein levels in B16 tumor cells after IFN-α or IFN-γ stimulation and found that IFN-γ was a more potent inducer than IFN-α for USP18 expression, as well as Stat1 phosphorylation, which is IFN-γ signaling downstream gene." (PMID 24884733, 2014). "In addition, the analysis of the GSE109211 dataset revealed a consistent upregulation of USP18 in tumor tissue samples obtained from HCC patients who exhibited a non-responsive phenotype towards sorafenib treatment." (PMID 40514377, 2025).
tumor (continued). "Compared with the control, depletion of USP18 significantly reduced tumour growth." (PMID 40374599, 2025). "Additionally, IHC analysis of tumour tissues from nude mice revealed that USP18 knockdown resulted in reduced expression of stemness markers (SOX2 and CD133) and a proliferation marker (KI67)." (PMID 40374599, 2025). "Similarly, IHC staining results showed that USP18 overexpression compromised the efficacy of sorafenib in inhibiting tumor cell proliferation." (PMID 40514377, 2025). "Furthermore, single-cell sequencing revealed that USP18 was significantly expressed mainly in tumor-infiltrating T cell subsets, especially in CD8+ T cells." (PMID 39334957, 2024). "Since the NLRP3 inflammasome can be formed and activated by DAMPs, PLK2-induced DAMP release could also be crucial for GSDMD pathway activation in the USP18-depleted tumor environment in vivo." (PMID 38799433, 2024). "In addition, high USP18 expression was positively correlated with the CRC survival rate and closely associated with tumor-infiltrating CD8+ T cells and natural killer (NK) cells." (PMID 39334957, 2024). "However, the oncogenic or tumour suppressive outcome of the USP18 varies based on the differing cellular and tumour contexts." (PMID 38939897, 2024). "The deubiquitinating enzyme USP18 is known to play an important role in various aspects of the immune response, but its role in tumor immunity in CRC remains unclear." (PMID 39334957, 2024). "Consequently, diminishing USP18 leads to an increase in anti-tumour macrophages within the tumour microenvironment." (PMID 38455765, 2024). "In addition, USP8, USP15, USP9X, and USP18 can directly bind to PD-L1, stabilizing PD-L1 expression and promoting immune evasion by tumor cells." (PMID 39315102, 2024). "Moreover, recent studies have shown that deletion of USP18 reduces tumor cell proliferation, migration, and invasion." (PMID 36771004, 2023). "Here, we show that deletion of USP18 in myeloid cells suppresses tumor progression." (PMID 38100351, 2023). "The effects on interferon signaling of USP18 also affects tumor progression." (PMID 37658402, 2023). "Another gene downregulated by ~nine-fold in GEN-treated TM4 cells is Usp18 (Ubiquitin specific protease 18), shown to promote proliferation and be negatively regulated by Wt1 (Wilms tumor gene), a transcription factor that plays a role in spermatogenesis and in inhibiting interferon signaling." (PMID 37443838, 2023). "This is, at least in part, a mechanism of enhanced anti-tumor activity observed in USP18-KO mice." (PMID 38100351, 2023). "Notably, some other studies have shown that USP18 has a strong tumor-promoting effect, indicating that USP18 functions through other important pathways besides de-ISGylase." (PMID 36771004, 2023). "We next assessed whether Usp18 depletion can exert an enhanced anti-tumor effect in combination with a treatment that increases IFN production." (PMID 36646704, 2023). "The clusters on this trajectory were increased by the deletion of Usp18, suggesting that the deletion of Usp18 may induce the reprogramming of TAMs toward an anti-tumor phenotype." (PMID 38100351, 2023). "Since the NLRP3 inflammasome can be formed and activated by DAMPs, PLK2-induced DAMPs release could also be important for GSDMD pathway activation in USP18 depleted tumor environment in vivo." (PMID 36646704, 2023). "In PDAC, USP18 was considered as a tumor promoter and possess significant prognostic value whose overexpression could promote cell proliferation through removing K48-linked ubiquitin from Notch-1 and activating Notch-1/c-Myc signaling pathway." (PMID 36582601, 2022). "Additionally, we confirmed low expression of USP18 protein and fewer aDCs in the tumor tissues of EN DLBCL patients by IHC staining." (PMID 34001679, 2021). "Moreover, the USP18 protein was confirmed to be expressed at low levels in tumor tissues of EN DLBCL patients by IHC staining." (PMID 34001679, 2021).
tumor (continued). "Indeed, forced expression of PYCR1 restored the propagation and invasion defects of FTO-depleted BLCA cells, indicating the essential tumor-promoting role of USP18/FTO/PYCR1 signaling network in BLCA." (PMID 33461172, 2021). "Indeed, the USP18 protein was confirmed to be expressed at lower levels in tumor tissues in patients with EN DLBCL than in those with LN DLBCL by immunohistochemistry." (PMID 34001679, 2021). "The role of USP18 in tumor microenvironment has begun to be demonstrated." (PMID 32957626, 2020). "Further, the protein content of USP18 was downregulated in siUSP18 tumours." (PMID 32770981, 2020). "After 5 weeks of growth, USP18-knockdown BxPC-3 cells (BxPC-3/shUSP18) exhibited reduced tumour growth in nude mice, whereas USP18-overexpressing SW1990 cells (SW900/p-USP18) exhibited significantly greater tumour growth compared with their respective controls." (PMID 33051403, 2020). "In addition, expression of USP18 in non-tumour tissues was negatively correlated with ALT levels (Spearman's rho= -0.33, P=0.03)." (PMID 32132870, 2020). "A previous report indicated that USP18 is increased in certain human tumours." (PMID 32770981, 2020). "This suggests that USP18 can act on type III IFN signaling, however this was in a tumor model and it is unclear if there whether other parts of the signaling cascade were disrupted in this model or if USP18 was expressed at higher than normal levels." (PMID 30901970, 2019). "Recent work also uncovered a potential tumor suppressive role for USP18 in FVB-Usp18 knockout mice." (PMID 27980214, 2017). "Moreover, ectopic USP18 expression in B16-OVA tumor cells significantly increased the CTL activity of activated OT-1 cells in vitro." (PMID 24884733, 2014). "All these reports suggested that USP18 may have both anti- and pro-oncogenic activity depending on the target cells in the tumor environment." (PMID 24884733, 2014). "USP18 also stabilize cyclin D of tumor cells to inhibit apoptosis." (PMID 24884733, 2014). "To investigate whether endogenous IFN signaling induces USP18 expression during tumor development in vivo, we inoculated C57BL/6 mice with B16-GFP tumor cells." (PMID 24884733, 2014). "Tumor microenvironment contains a variety of other cells, such as immune cells and stromal cells, and USP18 could regulate immune cells." (PMID 24884733, 2014). "Injection of Ad-USP18 significantly increased pmel-1 CTL activity and caused tumor shrinkage." (PMID 24884733, 2014). "Tumor cell USP18 expression was increased in vivo as compared with in vitro conditions." (PMID 24884733, 2014). "In conclusion, we found that IFN-γ signaling induces intrinsic expression of USP18 in tumor cells that not only affects tumorigenesis, but also may be useful in regulating immunotherapy efficacy." (PMID 24884733, 2014). "We speculated that USP18 expression in tumor cells might lead to secretion of soluble factors that also contribute to the immune activation." (PMID 24884733, 2014). "We found that USP18 is expressed in tumor cells after IFN-γ signaling stimulation." (PMID 24884733, 2014). "In our study, delivering USP18 into solid tumor could be accomplished by intra-tumor injection of adenovirus containing USP18 cDNA." (PMID 24884733, 2014). "Collectively, we show that the abundance of STAT2 and of USP18, in combination with information on patient‐specific IFNα levels allow us to propose with our calibrated mathematical model an IFNα treatment regime to prevent pathway desensitization and to optimize an antiviral or anti‐tumor response." (PMID 32696599, 2020). "However, the role of USP18 in the regulation of tumor cells is poorly understanded." (PMID 32742193, 2020). "Tumors of USP18 deficient mice also displayed an increased CD4+ T-cell infiltration, an increased level of cxcL-10 and hypersensitivity to IFN-λ enhanced up-regulation of CxcL-10 expression, which created a Th1/M1-polarized cytokine tumor environment and inhibited tumor progression." (PMID 29416786, 2018).
tumor (continued). "Thus, whether USP18 exerts an oncogenic or tumor suppressive effect depends on the tissue and cell contexts." (PMID 27980214, 2017). "Thus, classifying USP18 as an oncogenic or tumor suppressive species is likely cancer specific." (PMID 27980214, 2017). "As we found that endogenous IFN-γ signaling affected tumorigenesis through IFN-γ-induced USP18 expression in tumor cells and regulated immune-cell function in the tumor microenvironment, we wanted to explore whether USP18 expression in tumor cells affected exogenous IFN-γ-secreting CTL activity." (PMID 24884733, 2014). "Moreover, overexpression of USP18 in tumor cells may induce the immunesuppression activity of MDSC in tumor environment." (PMID 24884733, 2014). "However, it should be noted that in this study, USP18 expression in tumor cells not only affected tumor cell activity, but also regulated immune cells in tumor microenvironment in that tumor cell USP18 expression also activated CD11c+ dendritic cells residing in the tumor." (PMID 24884733, 2014). "Depletion of the negative regulator of type I IFN signaling USP18 in BMDMs or supplementation of IFN-β also decreased CD206 expression and scRNA-seq analyses underscored an anti-tumor polarization of macrophages due to USP18 deletion." (PMID 40098954, 2025). "The aim of the current study is to examine the function of USP18 and IFN-I in macrophages during tumor development by utilizing myeloid-lineage-specific USP18-knockout (KO) mice." (PMID 38100351, 2023). "Together, our data demonstrate that suppression of USP18 promotes UBCH5 and NEDD4-mediated proteasome degradation of CSF1R, leading to an increase in anti-tumor macrophages in the TME." (PMID 38100351, 2023). "To further analyze the function of USP18 in regulation of IFN response, we examined tumor growth with additional IFN stimulation by poly(I:C) treatment to stimulate endogenous IFN production." (PMID 38100351, 2023). "Our study showed that USP10, USP14, USP18, USP32, USP33, and USP39 (termed as six-USPs) expressions were significantly elevated in tumor tissues." (PMID 36582601, 2022). "The GEPIA results showed that the mRNA expression levels of USP18, IL2RA and IL21R were higher in tumor samples than in normal samples." (PMID 34001679, 2021). "At the cellular level, USP18, TLR7, IL21R, GCNT1 and CHST7 were expressed in various tumor cell lines, while the expression of LHX2, IL2RA and IL5RA was low in CCLE." (PMID 34001679, 2021). "In conclusion, we showed in the current study the abnormal USP18/FTO/PYCR1 signaling network in BLCA tissue, which favors cell proliferation and migration in vitro as well as tumor initiation and progression in vivo." (PMID 33461172, 2021). "Consistent with this, the average tumour weight in mice bearing BxPC-3/shUSP18 cells significantly decreased, whereas that in mice bearing SW900/p-USP18 cells obviously increased, when compared to those of the respective controls." (PMID 33051403, 2020). "In non-tumour tissues, EFP expression was strongly correlated with that of HERC5, UBA1 and USP18 (Spearman's rho =0.81, 0.89 and 0.75; P<0.0001, respectively)." (PMID 32132870, 2020). "Relative expression of the five genes EFP, HERC5, UBA1, UBC and USP18, which are related to ISGylation, was quantified and compared between HCC tumour and adjacent non-tumour tissues." (PMID 32132870, 2020). "As USP18 expression in tumor cells affects CD8+ T-cell function in vivo, B16-OVA-GFP or B16-OVA-USP18 cells were irradiated and then cocultured with OT-1 T cells in vitro to analyze T-cell activation." (PMID 24884733, 2014). "For instance, inhibition of the ubiquitin-specific peptidase Usp18 has been shown to increase miR-7 expression in several cancer cell lines, decreasing growth and cell survival, and thus a small molecule inhibitor of Usp18 may restore the tumor suppressor activity of miR-7 to cancer cells." (PMID 23115635, 2012).
tumor (continued). "However, the clinical relevance of USP18 in human CRC and its potential mechanisms in tumor immunotherapy remain to be fully elucidated." (PMID 39334957, 2024). "Finally, a significant reduction in tumor development was observed in the group of mice vaccinated with IFN-treated Usp18+/- cells, as assessed by the gold standard vaccination assay in B16F10 and MC38 tumor mouse models." (PMID 38799433, 2024). "Together, these results indicate that depletion of USP18 in myeloid cells enhances anti-tumor immune responses, which is not due to the increased protein modification by ISG15 and is likely related to the increased IFN-I response in the TME." (PMID 38100351, 2023). "In addition, due to knockdown of USP18, more T cell chemoattractant CXCL10 is generated in mammary epithelial cells, accompanied with creating a tumor-suppressive microenvironment by attracting CD4 + T cells." (PMID 37658402, 2023). "Strikingly, we observed a strong upregulation of PD-L1 on both tumour cells and T cells when USP18 was absent." (PMID 33214684, 2021). "USP18 depletion has been demonstrated to result in the high production of T cell chemoattractant C-X-C motif chemokine ligand 10 (CXCL10), which recruits CD4+ T cells and leads to the creation of a tumor-suppressive microenvironment." (PMID 32957626, 2020). "Here we show that expression of E3 ligases (HERC5 and EFP/TRIM25), UBA1 and USP18 is significantly upregulated in HCC tumours compared to adjacent non-tumour liver tissues." (PMID 32132870, 2020). "Multigene expression analysis by qRT–PCR revealed a strong correlation between the expression of human monocytic markers CD14 or CD16 and diverse IFN-I-related genes such as IFNB1, USP18 and IRF7, indicating that human monocytic infiltrates can produce IFN-I within human tumour tissues." (PMID 28248314, 2017). "To explore whether regulation of tumorigenesis by USP18 expression in tumor cells was due to host immune status, we intravenously inoculated B16-OVA-GFP or B16-OVA-USP18 tumor cells into NSG (NOD-SCID/IL2Rγ-/-) mice, which are deficient in T, B and NK cells." (PMID 24884733, 2014). "Ad-USP18 injection increased OT-1 CTL activity and tumor shrinkage." (PMID 24884733, 2014). "Using the PyVmT model of mammary tumourigenesis, we show that lack of the Usp18 gene significantly inhibits tumour growth by creating a tumour-suppressive microenvironment." (PMID 23681607, 2013). "Importantly, we previously reported that MCL1, IFITM1, and USP18 are co-expressed with STAT1 in the IR- and IFN-resistant nu61 tumor." (PMID 19503789, 2009). "Moreover, IFN fine-tunes immune activation by modulating the expression of ubiquitin-specific peptidase 18 (USP18), a key negative regulator of IFN signaling, which can prevent excessive immune activation and exhaustion, sustaining tumor cell sensitivity to immune surveillance." (PMID 41359111, 2025). "Additionally, USP18 may target PD-L1 through ISG15 and inhibit the growth of CRC in vivo, suggesting a potential strategy for targeting PD-L1-mediated immune escape in tumor cells." (PMID 39334957, 2024). "Notably, a recent study using established murine leukemia models have revealed that even a partial reduction of USP18 is sufficient to produce these anti-tumour effects without adversely impacting normal cells." (PMID 38455765, 2024). "Importantly, we find that this anti-tumor effect can be exerted by the heterozygous depletion of Usp18, which does not affect normal cells." (PMID 36646704, 2023). "Interestingly, tumor cell-derived proteins could affect the differentiation and function of DCs via the p38 MAPK pathway; thus, we speculated that USP18 might affect DC-modulating immune responses through the MAPK pathway in the development of EN DLBCL." (PMID 34001679, 2021). "In some USP18 knockout mice, dystrophic calcifications appeared with or without tumor development." (PMID 26555296, 2015).